INS (insulin)
Diseases named in the same sentence as INS in open-access papers (continued):
Sharing a sentence is not in itself a finding about the gene and the disease.
diabetes (continued). "Besides these clear links between diabetes and AD-related peptides and proteins, the physiological functioning of insulin and IGF promotes neuronal growth, differentiation, and the formation of synapses, the lack of which is associated with dementia." (PMID 32265649, 2020). "The acute effect of cinnamon on reducing 30 min post-prandial insulin and insulin niAUC may spares the pancreatic beta-cell and therefore might slow the progression of pre-diabetes to type 2 diabetes." (PMID 33553233, 2020). "Furthermore, it is still unclear if specific treatments capable of improving the insulin sensitivity of pancreatic α-cells can also control glucagon levels in patients with diabetes mellitus." (PMID 33020399, 2020). "Mitochondrial dysfunction of the insulin-producing β-cells might lead to β-cell apoptosis through the generation of free radicals and eventually to metabolic disorder and diabetes." (PMID 32102422, 2020). "Risk of death was assessed in Cox models adjusted for age, sex, race, heart rate, BMI, smoking, diabetes duration, insulin use, HbA1c, eGFR, brain natriuretic peptide (BNP), urine albumin/creatinine ratio, treatment allocation and prior coronary revascularization." (PMID 33046070, 2020). "Thus, retinal insulin signal transduction is impaired in the db/db mouse, similar to other models of diabetes." (PMID 32432228, 2020). "No other clinically relevant factors, such as insulin treatment and the duration of diabetes, were associated with GAD65Ab concentrations." (PMID 32378803, 2020). "The dose of oral hypoglycemic agents or insulin was reduced in 5 participants by their diabetes care providers, 4 participants’ insulin prescriptions were reduced by 6 to 24 units and 1 participant’s oral hyperglycemic agent prescription was reduced to a smaller dose." (PMID 32202506, 2020). "Studies have demonstrated that activation of neutrophils and macrophage results to oxidative stress as well as inflammatory cytokines release including IL-1β, IL-6 and TNF-α, leading to the decrease of insulin secretion, hepatic steatosis and a series of metabolic disorders in diabetes." (PMID 32028957, 2020). "There may not be as many advantages to point‐of‐care testing for those people with diabetes who are already using point‐of‐care devices to monitor blood glucose and self‐adjust their insulin." (PMID 31876039, 2020). "However, ghrelin treatment resulted in a marked (p < 0.04) increase in insulin serum levels in normal treated and diabetic treated (before and after the onset of diabetes) groups in comparison to their corresponding controls." (PMID 32325912, 2020). "We conclude that P4 increases hepatic glucose production via PGRMC1, which may exacerbate hyperglycaemia in diabetes where insulin action is limited." (PMID 33005004, 2020). "One potential option to improve diabetes control in these patients may be the use of new insulin formulations including second-generation basal insulin analogues such as insulin glargine 300 U/mL (Gla-300)." (PMID 32337298, 2020). "In diabetes mellitus (DM), chronic hyperglycemia may result from an impaired insulin secretion and/or resistance of key peripheral tissues to the effects of insulin." (PMID 32695007, 2020). "Developing a reliable glucose forecasting model would have a profound impact on diabetes management, since it could provide predictive glucose alarms or insulin suspension at low-glucose for hypoglycemia minimisation." (PMID 35415447, 2020). "In the population excluding study subjects with newly diagnosed diabetes mellitus (n = 33), forward stepwise regression modelling revealed age (r2 = 0.3995; p < 0.0001) and insulin clearance (r2 = 0.4685; p < 0.0001) as the most strongly and independently determinants associated with cIMT." (PMID 33384433, 2020).
diabetes (continued). "OT improves insulin sensitivity, increases lipolysis, enhances glucose uptake and lipid utilization in adipose tissue and skeletal muscle and plasma OT levels are notably lower in obese individuals with diabetes." (PMID 32082116, 2020). "Greater energy intake earlier in the day was associated with higher insulin sensitivity in individuals without diabetes." (PMID 32079066, 2020). "By comparing the differences in glycemic control between patients with different engagement levels in diabetes education courses, we found that diabetes education on the app platform was effective in diabetes management among patients with type 2 diabetes treated with insulin." (PMID 32141838, 2020). "Diabetes mellitus (DM) is a metabolic disorder characterized by hyperglycemia, with disturbances in the metabolism of carbohydrates, fat, and protein resulting from defects in insulin secretion, insulin action, or both." (PMID 31469700, 2020). "High levels of diabetes distress negatively affect insulin adherence and glycemic control." (PMID 32406854, 2020). "The combination of insulin, oral agents, and diet can partially reduce diabetes complications." (PMID 33905470, 2020). "This quality improvement study used retrospectively collected data on pediatric patients with a new diagnosis of diabetes who completed an inpatient program for education and insulin titration prospectively compared with patients completing a diabetes day hospital program." (PMID 32125428, 2020). "Elevation of fasting and PBG levels in diabetes are determined by distinct mechanisms of defective insulin secretion and/or signaling, and may occur independently of each other." (PMID 33195459, 2020). "Relevant studies suggest that the potential mechanisms of diabetes-induced AD might be due to dysregulation of glucose and insulin signaling in Type 2 DM." (PMID 32765958, 2020). "In diabetes, several factors drive a decline in beta cell mass including cellular stress due to compensatory insulin overproduction, glucotoxicity due to chronic hyperglycemia, lipotoxicity due to chronic high dietary SFA consumption, glucolipotoxicity, inflammation, autoimmunity and obesity." (PMID 33182622, 2020). "This statement was made a time when the commonest cause of death for a child with diabetes in Africa was lack of insulin." (PMID 32704558, 2020). "Additionally, we noted several phosphatidylinositols (PI) were positively associated with postpartum BMI; PI are important building blocks for cell signaling molecules in the insulin signaling pathway which also regulate diabetes, obesity and cell growth." (PMID 33291639, 2020). "For example, Pkfm expression is upregulated with diabetes, but normalized with insulin treatment." (PMID 33200530, 2020). "Therefore, when exercise is coupled with anti-diabetes medications including insulin or medications that promote insulin secretion (e.g., GLP-1 receptor agonists) it can result in hypoglycemia." (PMID 32349219, 2020). "Cytokine activates the production of ROS and reduction of insulin secretion which lead to diabetes." (PMID 32587797, 2020). "In addition, anti-insulin antibodies were found in the sera of naive C57BL/6 mice, which are susceptible to STZ-induced diabetes, reinforcing an autoimmune response in this model." (PMID 32295112, 2020). "Pathways activated by leptin in the brain have neuroprotective roles also, leptin may be a potentially useful adjunct to insulin treatment in management of diabetes." (PMID 33585009, 2020). "The intake of regular insulin is the major prevention for further effects of diabetes." (PMID 32215269, 2020). "The proportion of individuals with monogenic diabetes who receive insulin before their monogenic diabetes diagnosis—the larger the proportion receiving insulin before being diagnosed as having monogenic diabetes, the greater the costs saved for all strategies compared with No Testing." (PMID 32193268, 2020).
diabetes (continued). "However, when adjusting for insulin use in patients with diabetes only, PIPR was still a predictor of urinary aMT6s (results not shown)." (PMID 32005914, 2020). "Diabetes mellitus is a chronic disease of elevated blood glucose level due to either suboptimal production of insulin by the pancreas or peripheral resistance of the body to insulin." (PMID 32140428, 2020). "There are three convenient methods to treat diabetes, namely, oral hypoglycemic drugs, the subcutaneous injection of insulin or an insulin pump, while continual and long-term exogenous insulin is one of the most effective and safe ways for type-1 diabetes therapy." (PMID 34567719, 2020). "An interesting, though speculative finding of the reviewed literature was that the decrease in GV in response to acute exercise was present across the spectrum of diabetes duration as well as in patients using exogenous insulin treatment." (PMID 32903679, 2020). "Diabetes is known by a long term of hyperglycemia with disturbances in the metabolism of proteins, fats, and carbohydrates, which resulted from defects in insulin action and/or insulin secretion." (PMID 33415153, 2020). "Continuous insulin use varied significantly among centers from 8-100% in patients with diabetes." (PMID 33118731, 2020). "A number of studies have shown that the choice of travel destination by patients with diabetes may be affected by their use of insulin, and some of those patients avoid international travel altogether because of their disease." (PMID 32972370, 2020). "Insulin sensitivity is higher in women, who are also characterised by higher capacities for insulin secretion and incretin responses than men; although, these sex advantages all disappear when glucose tolerance deteriorates towards diabetes." (PMID 31754750, 2020). "Enrichment of the diet with ω-3 PUFA, e.g., by adding flaxseeds or flaxseed oil, may increase tissue sensitivity to insulin and prove effective in preventing diabetes." (PMID 33265987, 2020). "Insulin injection is the next option to treat patients with “resistant diabetes”." (PMID 32392806, 2020). "Type 2 diabetes mellitus (T2D) is a chronic metabolic disease resulting from insulin resistance and progressively reduced insulin secretion, which leads to impaired glucose utilization, dyslipidemia and hyperinsulinemia and progressive pancreatic beta cell dysfunction." (PMID 32961860, 2020). "The results from the OGTTs in animals supplemented with moringa, (improved glucose disposal, lower fasting insulin levels, and a trend towards greater nadir to peak insulin responses to oral glucose) are compatible with a metabolic profile that would lead to a delay in the onset of diabetes." (PMID 32483245, 2020). "Relief of glucotoxicity improves β-cell function, which could explain restoring normoglycemia after short-term intensive insulin treatment in patients with newly diagnosed diabetes." (PMID 32597475, 2020). "Therefore, our case has been in agreement with literature by concluding that insulin is in fact an effective and minimally invasive form to lower a high triglyceride level, especially in patients who have concurrent uncontrolled diabetes mellitus." (PMID 32832302, 2020). "The mechanisms of diabetes development in IMDs involve either defects of insulin secretion or insulin resistance, which might be promoted by liver or muscle involvement and oestrogen deficiency." (PMID 33179602, 2020). "As dysregulation of insulin biosynthesis is critical for the development of diabetes, interventions to modulate Ins2 expression by regulating ci-Ins2 function may be therapeutically valuable in the treatment of diabetes." (PMID 32560282, 2020). "Traditional medicines have great potential in the management of diabetes mellitus and the identification of active constituents that could enhance mitochondrial function and insulin signaling in skeletal muscle is an opportunity for the scientific community." (PMID 32987623, 2020).
diabetes (continued). "Importantly, there are no studies using hyperinsulinemic-euglycemic clamp (the gold-standard method to assess insulin sensitivity) or studies assessing incident diabetes from prediabetic subjects." (PMID 33287432, 2020). "It has been confirmed that dysregulated insulin levels in diabetes may impair the metabolism of homocysteine, resulting in elevated levels of this amino-acid." (PMID 32872672, 2020). "Regarding pre-existing comorbidities potentially associated with poor prognosis for COVID-19 disease, chronic lung diseases were the most prevalent (8.2%), followed by hypertension (6.2%), obesity (5.0%), diabetes (2.4%, with 0.6% of patients reporting insulin use) and heart disease (2.2%)." (PMID 33295428, 2020). "Finally, this study confirmed that whole WSP can be used to treat T2DM, by using experiments on mice with diabetes, biochemical analysis, histomorphometry, and insulin-signaling pathway analysis." (PMID 32425738, 2020). "In larger animal models, reduced absolute insulin secretion in encapsulated SC islets may result in reduced efficacy of diabetes reversal." (PMID 31839542, 2020). "Furthermore, diabetes type and severity, control of glucometabolic state, blood sugar levels before physical activity, the type of insulin or other hypoglycemic drugs, and their last assumption related to sport practice are relevant." (PMID 33467298, 2020). "Type 1 diabetes mellitus (T1DM) is an insulin-dependent, multifactorial autoimmune disease which results in degradation of the beta cells of islets of Langerhans, which causes impaired insulin production and secretion." (PMID 33008059, 2020). "Finally, the KEGG pathways analysis demonstrated the activity depletion of diverse diseases routes, like diabetes and acute myeloid leukemia, as well as insulin and calcium signaling pathways, in the knockout group." (PMID 32780740, 2020). "Type I diabetes mellitus (about 10% of cases of diabetes) is an autoimmune disorder that results from the progressive destruction of the insulin-producing beta cells of the pancreas by T cells and activated macrophages and eventually leads to insulin deficiency in the organism." (PMID 32911736, 2020). "For example, HbA1c and blood glucose concentrations are the principal biomarkers of diabetes, and measures of blood concentrations of insulin, proinsulin, lipids, inflammatory cytokines and adipokines are often used to study the determinants or consequences of diabetes." (PMID 32840675, 2020). "Human stem cell-derived SC-β cells develop into islet-like clusters comprised of cells that contain mainly insulin and, to a lesser extent, glucagon and somatostatin, and thus provide a unique opportunity to study diabetes in a human-derived cell culture system resembling native human islets." (PMID 32093375, 2020). "Among older adults without diabetes, insulin resistance was associated with aortic stiffness, but the putative role of insulin resistance in aortic stiffness over the life course requires further study." (PMID 31992297, 2020). "Finally, we performed a directed literature search combining the different KDs with the terms insulin, glucose, and diabetes." (PMID 33362275, 2020). "Furthermore, the applicability and personalization of the different glycemic monitoring devices used in specific insulin-treated diabetes mellitus patient populations will be evaluated." (PMID 33153229, 2020). "LH can significantly reduce the absorption of insulin by up to 25% and thus could worse diabetes control." (PMID 32071879, 2020). "Insulin secretagogues may also increase the load of islet cells and accelerate islet apoptosis; therefore, they cannot be applied to patients producing diabetes-related antibodies, cases such as latent autoimmune diabetes in adults (LADA)." (PMID 32656265, 2020). "In addition, it is shown that insulin drug preparations used for treating diabetes formed various types of amyloid aggregates that can be assessed and quantified using pFTAA and BTD21." (PMID 35515176, 2020).
diabetes (continued). "Notably, extreme carbohydrate restriction was commonly advised to patients with diabetes before the discovery of insulin." (PMID 33187118, 2020). "Advances in insulin’s molecular properties through new analogs, coupled with advances in glucose monitoring and dosing algorithms, will continue to make insulin therapy safer and more effective for people with diabetes." (PMID 32396624, 2020). "Insulin and other diabetes medications should be reviewed and adjusted as appropriate." (PMID 32743907, 2020). "We identified twelve metabolites to be associated with different indices of glucose metabolism and insulin sensitivity, in individuals without diabetes mellitus from the general population." (PMID 32124065, 2020). "Since emotions affect blood glucose and the course of diabetes, an impact which may directly be a result of the release of stress hormones that interfere with insulin regulation." (PMID 32252831, 2020). "What is more, adipokines may decrease the insulin sensitivity of tissues and induce inflammation and the development of atherosclerosis, diabetes and psoriasis, as well as diabetic foot." (PMID 32443588, 2020). "However, a large portion of research remained concentrated in cardiometabolic health including the study of insulin sensitivity/diabetes/weight gain/body mass index/metabolic syndrome, arterial stiffness and hypertension." (PMID 32645067, 2020). "The complexation of insulin with alginate and xanthan can be a new area of investigation for formulation preparations and drug delivery for a plethora of health problems including diabetes." (PMID 32050432, 2020). "This is relevant for these diseases as overweight and general low physical activity level promotes low insulin sensitivity, diabetes and metabolic syndrome, factors that may exacerbate the condition." (PMID 33234167, 2020). "However, the demand for the strict dietary option had been declined with the use of insulin as a therapeutic option for diabetes." (PMID 32640608, 2020). "The data on the ability of HSA to bind various compounds prompted us to undertake research on the use of HSA as a system capable of transporting peptidic inhibitors of insulin and amylin aggregation (both of these hormones are present in the amyloid deposits identified in people with diabetes)." (PMID 32992893, 2020). "To test these hypotheses, we recruited hospitalized insulin-treated diabetes patients presenting with hypertensive crisis at admission." (PMID 33292431, 2020). "In patients with diabetes, the insulin response to GLP-1 is blunted." (PMID 32308645, 2020). "In people with type-2 diabetes mellitus, a lower zinc concentration may influence the capacity of pancreatic cells to synthesize and secrete insulin." (PMID 33299532, 2020). "Thus, the administration of insulin is a factor that influences the decision to fast for people with diabetes." (PMID 33226993, 2020). "Of these patients, 265 (62.8%)were men, 128(30.3%) current consumed alcohol, 149(35.3%) had a history of current smoking, 414 (98.4%) had type 2 diabetes, and 230 (54.5%)used insulin; the mean duration of diabetes was 9.7 ± 7.7 years, and the mean duration of DFU was 57.6 ± 78.6 days." (PMID 32414389, 2020). "Type 2 diabetes mellitus is a chronic metabolic disease resulting from insulin resistance and progressively reduced insulin secretion, which leads to impaired glucose utilization, dyslipidemia and hyperinsulinemia and progressive pancreatic beta cell dysfunction." (PMID 32961860, 2020). "Additional studies show that in patients with impaired glucose balance, benzafibrate may delay progress of diabetes by improving insulin sensitivity, inhibiting atherosclerosis, and preventing ischemic heart injury." (PMID 32340373, 2020). "High UA accelerates but does not cause diabetes because UA itself is insufficient to induce diabetes although it can damage glucose tolerance, leading to insulin resistance." (PMID 33304270, 2020).